SMAD3 (SMAD family member 3)
Diseases named in the same sentence as SMAD3 in open-access papers (continued):
Sharing a sentence is not in itself a finding about the gene and the disease.
Autoimmunity (5 papers, 2014 to 2025). The occurrence of an immune reaction against the organism's own cells or tissues. "Known for its vital role in autoimmunity, SMAD3 can control the activation of the TGF-β receptor, thereby influencing the differentiation of T cells into Th17 cells, and ultimately impacting the immune response." (PMID 38075038, 2023). "Increased induction of Smad3 by Ash1l subsequently facilitates Foxp3 expression, contributing to the polarization of Treg cells and prevention of autoimmunity." (PMID 28598443, 2017). "As the activin A/Smad3 axis is conserved in human macrophages, it may be targeted to harness new therapeutic strategies during infections and autoimmunity." (PMID 40067393, 2025).
Cerebral ischemia (5 papers, 2019 to 2025). Restriction of arterial blood supply to the brain associated with insufficient oxygenation to support the metabolic requirements of the tissue. "Taken together, these findings demonstrated that the Arip1 deficiency attenuated neuronal ferroptosis after cerebral ischemia by increasing endogenous Act A levels, thereby modulating the Act A/SMAD3 and p38 MAPK signaling pathways, ultimately influencing the SLC7A11/GPX4 pathway." (PMID 40965963, 2025). "Moreover, we found that the deficiency of Arip1−/+ exerted a neuroprotective effect on brain ischemia through the inhibition of ferroptosis, which activates the Act A/SMAD3 and inhibits p38 MAPK signaling pathways." (PMID 40965963, 2025). "It has been reported that brain ischemia leads to the inhibition of the Act A/SMAD3 pathway and the activation of the p38 MAPK pathway, both of which perform essential roles in neuronal apoptosis following ischemic injury." (PMID 40965963, 2025). "There were 198 TFs identified after 6 h MCAO operation, and six TFs (Sox2, Smad3, FoxO1, Creb1, Egr,1 and Smad4) were considered as critical TFs in response to cerebral ischemia." (PMID 33414894, 2020). "Furthermore, after cerebral ischemia, the level of p‐SMAD3 was significantly increased while that of p‐p38 was markedly decreased in Arip1−/+ mice compared with those of WT rodents." (PMID 40965963, 2025). "In a rat model of cerebral ischemia/reperfusion, SMAD3 administration may downregulate inflammatory and proapoptotic genes, suggesting that the TGF-β/SMAD pathway is a possible drug target." (PMID 34829993, 2021). "Further validation of Smad3 reveals that Smad3 were putative targets of BNC and DHI against cerebral ischemia, indicating a different medication may regulate common transcriptional unit through synergy between Smad3 and other TFs." (PMID 33414894, 2020). "TGF expression was increased in an undifferentiated SH-SY5Y cell model of cerebral ischemia, together with increased phosphorylation of SMAD2 and SMAD3." (PMID 37380886, 2023). "Further validation indicated that Smad3 and other five TFs are putative target TFs for DHI and BNC against cerebral ischemia." (PMID 33414894, 2020). "Moreover, validation results indicated that Smad3 was a putative target TF for DHI and BNC-mediated protection against cerebral ischemia." (PMID 33414894, 2020). "Recent studies revealed that both SMAD3 and p38 MAPK signaling are involved in cerebral ischemic injury, but the relationship between activin A and these signals is not clear in models of adult cerebral ischemia." (PMID 40965963, 2025).
chronic pancreatitis (5 papers, 2022 to 2025). A chronic inflammatory process causing damage and fibrosis of the pancreatic parenchyma. "The neuronal transcription factor Pou4f1 has been identified as a Smad3 target gene in bone marrow-derived macrophages stimulated by transforming growth factor-beta 1 (TGF-β1), implicating the TGF-β1/Smad3 axis in nociceptive signaling in chronic pancreatitis." (PMID 41163091, 2025). "Smad3 has been suggested to regulate neural lineage commitment of multipotent neural stem cells and nociception in chronic pancreatitis." (PMID 36206343, 2022). "By recovering exocrine pancreatic function (PABA) and dropping TGF-β1, TGFβRII, and the Smad3 protein level, SSHT was also verified as a chronic pancreatitis therapy in rats." (PMID 37895842, 2023). "TGF-β and its canonical downstream effector Smad3 also regulate the nociceptive pain in chronic pancreatitis, suggesting an unexplored role of TAMs in the TGF-β1/Smad3–driven neurogenesis." (PMID 36206343, 2022).
depression (5 papers, 2019 to 2025). "In our population of patients with pathogenic variants in the SMAD3 gene, 4% scored above the cut‐off for clinical anxiety, while 7% scored in the range for clinical depression." (PMID 31132219, 2019). "Inactivation of Smad3 in animal models of depression induced by chronic restraint stress reveals TGF-β/Smad3 signalling together with non-canonical pathway components such as TAK1 and Erk play potential roles in hippocampal neurogenesis." (PMID 34205102, 2021).
Hepatic steatosis (5 papers, 2019 to 2025). Steatosis is a term used to denote lipid accumulation within hepatocytes. "Conversely, adipocyte deletion of SMAD3 protects mice from obesity, diabetes, and hepatic steatosis." (PMID 40301996, 2025). "Earlier, we had observed a liver-specific role of the Smad3 adaptor βII-spectrin in response to the diet-induced fatty liver through its interactions with the lipogenic transcription factor SREBP1." (PMID 38323119, 2024). "Blocking TGF-β signaling genetically (SMAD3−/−) and pharmacologically (anti-TGF-β antibody, 1D11) in mice lead to protective effects: decreased body weight gain and fat mass, improved insulin sensitivity, ameliorated hepatic steatosis." (PMID 40301996, 2025). "Despite having persistent hepatic steatosis, offspring born to Tg parents showed an improved balance of hepatic glucose/lipid metabolic markers, as well as reduced levels of inflammatory markers and TGF-β/Smad3 fibrotic signalling." (PMID 33027895, 2020).
hypertensive heart disease (5 papers, 2021 to 2024). Abnormal enlargement of the heart resulting from long-standing hypertension. "Moreover, Smad3 deficiency is also reported to inhibit angiotensin II‐induced hypertensive cardiovascular diseases." (PMID 33733577, 2021). "This suggests that inhibition of Smad3-dependent molecules specifically associated with cardiac fibrosis, rather than targeting the entire TGF-β/Smad3 signaling, may be a better approach to treat hypertensive cardiovascular disease." (PMID 37449045, 2023).
hyperuricemia (5 papers, 2017 to 2024). An abnormally high level of uric acid. "PP1 treatment also inhibited hyperuricemia-induced activation of the TGF-β1/Smad3, STAT3, ERK1/2, and NF-κB signaling pathways and expression of multiple profibrogenic cytokines/chemokines in the kidney." (PMID 38576481, 2024). "BET inhibition also inhibited hyperuricemia–induced activation of TGF-β/Smad3, NF-κB and ERK1/2 signaling pathways." (PMID 33664670, 2021). "We found hyperuricemia induced epithelial‐to‐mesenchymal transition (EMT) of cultured human peritoneal mesothelial cells by activating TGF‐β1/Smad3 signalling pathway and nuclear transcription factors." (PMID 34309202, 2021). "Accumulating evidences indicated hyperuricemia was a risk factor for CKD and several mechanisms have been suggested including the uric acid induced epithelial-to-mesenchymal transition (EMT) of renal tubular cells, activation of TGF-β/Smad3 pathway and increased renal oxidative stress." (PMID 29340054, 2017). "In this study, we demonstrated that treatment with I-BET151 diminished hyperuricemia-induced TGF-β1 expression and phosphorylation of Smad3." (PMID 33664670, 2021). "In one study, investigating hyperuricemia in rats, the pharmacological inhibition of ERK1/2 resulted in a significant reduction in the Smad3-dependent renal pathology." (PMID 34769237, 2021).
ischemic stroke (5 papers, 2021 to 2026). A stroke disorder caused by obstruction of blood flow to the brain, due to thrombotic (local blood clot formation) or embolic (due to a blood clot or other material traveling from another site) event. "Schematic representation of the effect of EA on microglial polarization induced inflammation by regulating the TGF‐β/Smad‐3 signaling pathway in ischemic stroke mice." (PMID 40831324, 2025). "Salidroside could activate the TGF-β1/Smad3 signaling pathway in ischemic stroke model mice, inhibit Bax expression, and promote the expression of Bcl-2, TGF-β1, and p-Smad3, thereby reducing the damage of nerve function and playing a protective role on nerve cells." (PMID 33981351, 2021).
keratoconus (5 papers, 2018 to 2024). A degenerative, structural disorder of the eye, characterized by a cone-shaped protrusion of the cornea. "Although CPLX2 (ranked number 16 by Watson) showed a marginally significant association with keratoconus, only SMAD3 (with the highest similarity score) showed a robust association with keratoconus." (PMID 32737415, 2020). "We also identified SMAD3 rs12913547 as a susceptibility locus for keratoconus development using predictive analysis with IBM’s Watson question answering computer system (P = 0.001)." (PMID 32737415, 2020). "Indeed, most CCT-reducing alleles have been associated with an increased risk of keratoconus, and this was true for SMAD3 rs12913547 in the current study." (PMID 32737415, 2020). "WDD analysis assisted in identifying another keratoconus-susceptibility SNP, i.e. SMAD3 rs12913547." (PMID 32737415, 2020). "FOXO1 is a well-established susceptibility gene for keratoconus, while the association of SMAD3 with keratoconus susceptibility remains unclear." (PMID 30127857, 2018). "Although a SNP in SMAD3 only showed nominal significance in association with keratoconus in the same study, it is possible that other SNPs might confer the risk, and further fine mapping approach is required to get the whole picture of this region." (PMID 30127857, 2018). "We found evidence that SNPs associated with keratoconus often alter methylation of many genes, including LOX, PDDC1, SMAD3, HOXB1, KLF5, and BANP." (PMID 33649486, 2021). "Specifically, we selected seven keratoconus-susceptibility genes (CDH13, SMAD3, ADAM12, CSMD1, NRXN1, CPLX2, and WWOX) for further analysis." (PMID 32737415, 2020). "In summary, we identified two keratoconus-susceptibility loci, STON2 and SMAD3, by integrating conventional GWAS and artificial intelligence, using WDD." (PMID 32737415, 2020). "Through WDD, we identified SMAD3 as an additional keratoconus-susceptibility gene (OR = 1.44 (1.16–1.80), P = 0.001), and CPLX2 as a future candidate gene for keratoconus-susceptibility (OR = 0.70 (0.46–1.05), P = 0.082)." (PMID 32737415, 2020). "They found the STON2 rs2371597 and SMAD3 rs12913547 loci to be involved in keratoconus development." (PMID 38984114, 2024). "STON2 and SMAD3 have roles in extracellular matrix (ECM) remodeling, so these variants may contribute to the stromal ECM changes described in keratoconus." (PMID 38984114, 2024). "Further studies of the roles of SMAD3, FOXO1, and TGF-β signalling in keratoconus development are needed." (PMID 32737415, 2020).
leiomyoma (5 papers, 2014 to 2026). A well-circumscribed benign smooth muscle neoplasm characterized by the presence of spindle cells with cigar-shaped nuclei, interlacing fascicles, and a whorled pattern. "Research shows Vitamin D3 stops TGF-β3 from activating Smad2 phosphorylation and prevents Smad2 and Smad3 from entering the nucleus in leiomyoma cells." (PMID 41514933, 2026). "Tissue from UL has been shown to overexpress receptor‐activated SMAD3, common SMAD4 and TGF‐βRs in leiomyoma, compared to the myometrium." (PMID 35118811, 2022). "The expression of SMAD3, SMAD4 and phosphorylated SMAD3, as well as TGF-βR type I and type II, were all higher in leiomyoma when compared with those in myometrium." (PMID 25295107, 2014). "Additionally, gonadotropin‐releasing hormone analog (GnRHa) therapy decreases TGF‐βRs, SMAD3 and SMAD4 along with an increase in SMAD7 expression in both myometrium and leiomyoma tissues compared to untreated control." (PMID 35118811, 2022).
lung diseases (5 papers, 2014 to 2025). "A number of these genes have reported associations with COPD or other pulmonary diseases and include; CYP2E1, HEY1, SMAD3, BARD1 and FOXP1." (PMID 31860681, 2019). "Moreover, TGF-β1 enhances phosphorylation of Smad2 and Smad3 in cells, leading to the TGF-β-dependent EMT and subsequent development and progress of fibrosis-related lung diseases." (PMID 27271612, 2016).
lymphoma (5 papers, 2017 to 2025). A malignant (clonal) proliferation of B- lymphocytes or T- lymphocytes which involves the lymph nodes, bone marrow and/or extranodal sites. "SMAD3 (ENSP00000332973), as the next predicted biomarker, has been associated with lymphoma by multiple independent publications." (PMID 34899868, 2021). "In conclusion, combination treatment of curcumin with HHT exerted anti-lymphoma effects in Raji cells by inactivating the TGF-β/Smad3 pathway." (PMID 34324434, 2021). "Consistent with these previous findings, we found that combination treatment decreased Smad3 phosphorylation and reduce nuclear accumulation of Smad4 in lymphoma cells in vitro and in vivo." (PMID 34324434, 2021). "Our findings indicate that combination of HHT and curcumin inhibited lymphoma cell growth by downregulating the TGF-β/Smad3 pathway." (PMID 34324434, 2021). "Analytical results indicated that some inferred genes, such as RAC3, TEC, IRAK2/3/4, PRKCE, SMAD3, BLK, TXK, PRKCQ, were associated with the initiation and progression of lymphoma." (PMID 34899868, 2021). "This identified upregulation of TGFβ signalling as the most affected molecular pathway in Eμ-Myc;shBcor lymphomas (Bonferroni corrected P=0.0058), with enhanced expression of TGFβ pathway members (Cited1, Bambi, Acvr2b, Smad3, Mapk12, Tgfb2)." (PMID 28262675, 2017). "The analytical results showed that some of these genes (RAC3, TEC, IRAK2/3/4, PRKCE, SMAD3, BLK, TXK, PRKCQ) could be novel lymphoma-associated genes." (PMID 34899868, 2021). "Moreover, this combination treatment suppressed migration and invasion and induced apoptosis of lymphoma cells by inhibiting the TGF-β1/Smad3 pathway." (PMID 34324434, 2021). "In this study, we found that HHT combined with curcumin could exert tumoricidal effects in lymphoma cells in vitro and in vivo via inhibition of TGF-β/Smad3 signaling pathway." (PMID 34324434, 2021).
psoriasis (5 papers, 2015 to 2025). An autoimmune condition characterized by red, well-delineated plaques with silvery scales that are usually on the extensor surfaces and scalp. "This was associated with an increased ability of the reconstituted macrophages to produce IL-6, confirming that Smad3-deficient macrophages are indeed proinflammatory in the context of psoriasis." (PMID 40067393, 2025). "While the exact role of TGF-β in the pathogenesis of psoriasis is not completely understood, data available so far suggests that it might be a good biomarker for the severity of psoriasis and treatments targeting Smad3 might be associated with favorable results." (PMID 30744173, 2019). "We next used the IMQ-induced psoriasis model in mice to study the role of the activin A/Smad3 pathway in macrophages in the regulation of the disease." (PMID 40067393, 2025). "Interestingly, upon IMQ application, Smad3-KO BM chimeras had exacerbated psoriasis development as exemplified by increased skin thickness." (PMID 40067393, 2025). "Our results confirm that UVB irradiation inhibits IL-17A/TNF-α-induced IL-6, IL-8, and CXCL-1 production in HDFs by decreasing the expression of IL-17RA and IL-17RC on fibroblasts through TGF-β1/Smad3 pathway, which reveals a new mechanism of the therapeutic action of UVB on psoriasis." (PMID 28217129, 2017). "UVB irradiation inhibits IL-17A/TNF-α-induced IL-6, IL-8, and CXCL-1 production in HDFs by decreasing the expression of IL-17RA and IL-17RC on fibroblasts through TGF-β1/Smad3 signaling pathway, which reveals a new mechanism of the therapeutic action of UVB on psoriasis." (PMID 28217129, 2017).
thyroid cancer (5 papers, 2017 to 2023). "The SMAD family member 3 gene (SMAD3) shows higher expression in the thyroid than in the majority of other tissues, supporting a potential role for this factor in predisposition to thyroid cancer." (PMID 31247975, 2019). "Further, these authors investigated the downstream mechanisms by which alterations of SMAD3 contribute to thyroid cancer susceptibility." (PMID 31247975, 2019). "In thyroid cancer cells, oncogene activation prevented TGF-ß/SMAD-dependent p27 repression and CDK2/SMAD3 phosphorylation, leading to p65 up-regulation, which repressed BAX, induced cyclin D1 and promoted TGF-ß-dependent growth." (PMID 37954148, 2023).
type 1 diabetes (5 papers, 2021 to 2023). "Taken together, all these findings suggest that Smad3 deficiency largely promotes β cell proliferation, thereby restoring euglycemia in STZ-induced type-1 diabetes." (PMID 34987651, 2022). "In addition, Smad3-deficient mice demonstrated reduction in both renal and cardiac fibrosis in STZ-induced type 1 diabetes and in obese diabetic mice." (PMID 36313337, 2022).
Atrophy (4 papers, 2008 to 2022). Any weakening or degeneration, especially through lack of use. "Therefore, SMAD3 immunoreactivity was a characteristic signature of morphologically preserved cortical and medullar distal tubules and collecting ducts and was not related to chronic renal parenchymal damages (interstitial fibrosis and tubular atrophy)." (PMID 30383875, 2018). "In this perspective, we think that our approach has given a good contribution: in fact we were able to identify some proteins and transcription factors, such as SMAD3/4, GNB2L1/RACK1, MYC, MAX and JUN whose functions have been studied extensively in tumours and in some atrophy models." (PMID 19108710, 2008).
brain tumor (4 papers, 2023 to 2025). "Also, the inhibition of HDAC2 activity disrupted the interaction with SMAD3, resulting in the loss of stem cell-like characteristics of brain tumor cells." (PMID 39063083, 2024). "Although SMAD3 is an important component of transforming growth factor (TGF)-β signaling, the JICD1/SMAD3 transcriptional complex was shown to govern brain tumor invasion independent of TGF-β signaling." (PMID 38092725, 2023).
chronic heart failure (4 papers, 2021 to 2025). "Interestingly, in animal studies in rabbits with chronic heart failure (CHF), CCM led to the significant downregulation of TGF-β1 and Smad3, which was associated with reduced collagen deposition and fibrosis, which in turn could be a molecular explanation for the improvement of diastolic function." (PMID 40648858, 2025).
chronic myeloid leukemia (4 papers, 2014 to 2024). "There was a marked increase in the levels of total SMAD3 and phosphorylated-SMAD3 in Berbamine-treated chronic myeloid leukemia cells." (PMID 35269900, 2022).
congenital heart disease (4 papers, 2014 to 2025). A heart disease that is present at birth. "While other congenital heart defects such as persistent ductus arteriosus, atrial septal defect, and pulmonary valve stenosis have been observed in patients with SMAD3 mutations, to our knowledge, this is the first case reported with HLHS." (PMID 24711937, 2014). "The aim of this work was to find evidence on whether SMAD3 variations might be associated with ventricular septal defects (VSD) or other congenital heart diseases (CHD)." (PMID 26110764, 2015). "SNP rs2289263 before 5’UTR of SMAD3 gene associated with the risk of ventricular septal defect not congenital heart diseases in Chinese populations." (PMID 26110764, 2015).